PSIP1 (PC4 and SRSF1 interacting protein 1)
Description:
Transcriptional coactivator involved in neuroepithelial stem cell differentiation and neurogenesis. Involved in particular in lens epithelial cell gene regulation and stress responses. May play an important role in lens epithelial to fiber cell terminal differentiation. May play a protective role during stress-induced apoptosis. Isoform 2 is a more general and stronger transcriptional coactivator. Isoform 2 may also act as an adapter to coordinate pre-mRNA splicing. Cellular cofactor for lentiviral integration.
Synonyms: DFS70; LEDGF; PSIP2; p52; p75; PAIP
Tractability: Small molecule: a structure with a bound ligand is known. PROTAC: UniProt records ubiquitination sites on it; ubiquitination databases record sites on it; its protein half-life has been measured; a small molecule that binds it is known.
Target class: Reader; Methyl-lysine/arginine binding protein; Epigenetic regulator; PWWP domain
Gene: Protein-coding gene on chromosome 9 (15,464,065 to 15,511,202, reverse strand). Ensembl gene ENSG00000164985.
Subcellular location: Nucleus
Subcellular location (Human Protein Atlas): Nucleoplasm
Pathways (Reactome):
Disease: 2-LTR circle formation; APOBEC3G mediated resistance to HIV-1 infection; Autointegration results in viral DNA circles; Integration of provirus; Integration of viral DNA into host genomic DNA; Vpr-mediated nuclear import of PICs
Gene expression (Transcription): Formation of WDR5-containing histone-modifying complexes
Gene Ontology:
Molecular function: protein binding; RNA binding; supercoiled DNA binding
Biological process: mRNA 5'-splice site recognition; chromatin remodeling; response to heat; response to oxidative stress
Cellular component: nucleoplasm; cytosol; euchromatin; nucleus
Genetic constraint (gnomAD): Loss-of-function variants: 10 observed, 42.76 expected, observed/expected ratio (o/e) 0.23, 90% interval 0.14 to 0.4. The upper end of that interval is the gene's LOEUF score, 0.4, which puts it in group 1 of 6, group 1 being the genes least tolerant of losing a copy. Missense variants: 402 observed, 425.43 expected, observed/expected ratio (o/e) 0.94, 90% interval 0.87 to 1.03. Synonymous variants: 151 observed, 141.77 expected, observed/expected ratio (o/e) 1.07, 90% interval 0.93 to 1.22.
Cancer hallmarks: genome instability and mutations (suppresses); escaping programmed cell death (promotes); invasion and metastasis (promotes)
Homologues: Orthologues: chimpanzee PSIP1 (100% identical), pig PSIP1 (98% identical), macaque PSIP1 (96% identical), rabbit PSIP1 (96% identical), guinea pig PSIP1 (95% identical), mouse Psip1 (92% identical), rat Psip1 (92% identical), tropical clawed frog psip1 (63% identical), dog PSIP1 (42% identical), zebrafish psip1a (36% identical), zebrafish psip1b (31% identical), dog PSIP1 (30% identical). Paralogues in human: HDGFL2 (36% identical), HDGF (19% identical), HDGFL3 (18% identical), HDGFL1 (15% identical).